ALDH2 (aldehyde dehydrogenase 2 family member)
Diseases named in the same sentence as ALDH2 in open-access papers (continued):
Sharing a sentence is not in itself a finding about the gene and the disease.
alcoholism (continued). "In contrast, environmental factors, such as cultural attitudes that emphasize abstinence or moderate alcohol consumption, can protect against the development of alcoholism in the absence of alcohol use, when genetic factors, such as the ALDH2 gene, likely have no influence." (PMID 31798054, 1995). "Our study revealed that the ALDH2 rs671 polymorphism (GA/AA genotype) was significantly associated with the incidence and risk of HCC and mortality compared with the GG genotype in patients with cirrhosis with alcoholism regardless of their HBV infection status." (PMID 35877121, 2022). "In ALDH2*1/*1 individuals (i.e., ALDH2*1 homozygotes), one ADH1B*2 allele was associated with about one-fourth (OR = 0.26) and two ADH1B*2 alleles were associated with about one-fifth (OR = 0.20) the risk of alcohol dependence compared with individuals with no ADH1B*2 alleles." (PMID 27163368, 2016). "When the combination of the current flushing, ALDH2*1/*2, and ADH1B*2/*2 was used as a reference, the never or former flushing was markedly increased the ORs of alcohol dependence in the carriers of each ALDH2 and ADH1B genotype combination." (PMID 34310648, 2021). "On the other hand, ALDH2 “GG” genotype and AST elevation (suggesting heavy alcohol drinking but not necessarily alcoholism) were significantly outcome predictors." (PMID 31737110, 2019). "ADH2, ADH3, ALDH2, and CYP2E1 genotypes a population of 148 individuals with non-problematic alcohol and 65 individuals with alcoholism were determined with TaqMan probes and PCR-RFLP." (PMID 26848198, 2015).
esophageal cancer (85 papers, 2009 to 2026). A primary or metastatic malignant neoplasm involving the esophagus. "A substantial proportion of the Japanese population carries the aldehyde dehydrogenase 2*2 (ALDH2*2) allele, which impairs ALDH2 enzymatic activity and increases acetaldehyde exposure, thereby elevating esophageal cancer risk." (PMID 41996377, 2026). "It is well known that this variant reduces the enzymatic activity of ALDH2, causing alcohol flushing and intolerance, and has been associated with increased risks of cardiovascular diseases and esophageal cancer." (PMID 40699860, 2025). "In particular, individuals carrying the low-activity ALDH2*2 variant are prone to acetaldehyde accumulation, even with small amounts of alcohol, placing them at an increased risk of esophageal cancer, liver cirrhosis, and head and neck cancers." (PMID 40943250, 2025). "Alcohol consumption is a causative factor in human cancer development, particularly emphasized in the well-investigated relationship between ALDH2 polymorphism, rs671, and esophageal cancer risk." (PMID 40563518, 2025). "As mentioned in the introduction, about half of Japanese have heterozygous ALDH2*1 and ALDH2*2 and are at significantly high risk of alcohol-related head and neck and/or esophageal cancer." (PMID 38894937, 2024). "East Asia also has the highest world-wide incidence of esophageal cancer; likely due to the high frequency of the ALDH2*2 variant." (PMID 39075523, 2024). "Of the discovered loci, four (GCKR, ADH1B, ALDH1A1, and ALDH2) were suggested to interact with rs671 in the risk of esophageal cancer, a representative alcohol-related disease." (PMID 38277453, 2024). "Of these, four (GCKR, ADH1B, ALDH1A1, and ALDH2) were found to potentially interact with rs671 on the risk of esophageal cancer." (PMID 38277453, 2024). "The researches have shown that ALDH2 gene polymorphism is closely related to the occurrence of gastric cancer, esophageal cancer, and other cancers." (PMID 39132147, 2024). "A similar example of heterozygosity associated with disease development was reported in the association between aldehyde dehydrogenase 2 (ALDH2) gene mutation and esophageal cancer." (PMID 37304843, 2023). "The aldehyde degrading function of the ALDH2 enzyme is impaired by Glu504Lys polymorphisms (rs671, termed A allele), which causes alcohol flushing in east Asians, and elevates the risk of esophageal cancer among habitual drinkers." (PMID 36345163, 2023). "Polymorphisms in ALDH2 increased the risk of esophageal cancer with exposure to ethanol and cigarette smoking." (PMID 37641095, 2023). "It has been shown that ALDH2 SNPs are associated with higher levels of smoking–DNA adducts in blood with higher rates of esophageal cancer and with lung cancer in smokers." (PMID 34940794, 2022). "Accumulation of acetaldehyde due to alcohol consumption or aldehyde dehydrogenase (ALDH2) deficiency increases the risks of various types of cancers, including esophageal cancer." (PMID 35717470, 2022). "Genetic polymorphisms of ADH1B, ADH1C and ALDH2 have been reported involving in the development and progression of many cancers, such as gastric cancer, head and neck cancers, esophageal cancer, and pancreatic cancer." (PMID 35280985, 2022). "Previous Japanese studies noted that genetic variants in ALDH2 are involved in ethanol metabolism, specifically associated with the risk of esophageal cancers." (PMID 36289279, 2022). "ALDH2 gene polymorphism displays a close relationship to the susceptibility of colorectal cancer, esophageal cancer, liver cancer and other cancers." (PMID 36523602, 2022). "According to a previous report, people with ALDH2*2 variants have higher risks of head and neck and esophageal cancers, because the ALDH2 activity in their tissues is much lower compared to that in the gastrointestinal tissues of healthy people." (PMID 34010294, 2021). "In this study, we found that the ALDH2 GA/AA genotype is associated with a high risk of esophageal cancer." (PMID 33750341, 2021).
esophageal cancer (continued). "An exploratory genome-wide association study (GWAS) revealed that ALDH2 rs671 polymorphisms were associated with esophageal cancer." (PMID 33750341, 2021). "In men, the association between ALDH2 polymorphisms and esophageal cancer was modified by alcohol consumption." (PMID 33750341, 2021). "In accordance with our findings, previous studies reported a relationship between the ALDH2 GA/AA genotype and the risk of esophageal cancer." (PMID 33750341, 2021). "In the present study, we evaluated the association between ALDH2 rs671 polymorphisms and the risk of esophageal cancer in the South Korean population." (PMID 33750341, 2021). "For example, esophageal cancer is less common among ALDH2*2 carriers due to reduced drinking habits, but ALDH2*2 carriers with drinking habits show the highest risk because of accumulated aldehydes." (PMID 34022841, 2021). "Age-adjusted logistic regression analysis was performed to assess the association between ALDH2 rs671 polymorphisms and esophageal cancer." (PMID 33750341, 2021). "Patients with ALDH2 deficiency who cannot decompose acetaldehyde, the primary metabolite of ethanol contained in alcoholic beverages, are at high risk of esophageal cancer if they drink habitually." (PMID 33826001, 2021). "In men, the association between ALDH2 rs671 polymorphisms and esophageal cancer differed significantly based on alcohol consumption (P < 0.001)." (PMID 33750341, 2021). "This is the first study to evaluate the association between ALDH2 rs671 and esophageal cancer in the South Korean population." (PMID 33750341, 2021). "Nevertheless, the association between ALDH2 polymorphisms and esophageal cancer remains under debate." (PMID 33750341, 2021). "In the Kadoorie Biobank cohort, individuals with minor allele of ALDH2 rs671 polymorphism presented high risk of esophageal cancer, and the impact of ALDH2 polymorphisms on esophageal cancer risk was higher among individuals who consumed alcohol." (PMID 33750341, 2021). "Such ALDH2 mutations are common in East Asians and linked to esophageal cancer susceptibility in alcohol users." (PMID 32966340, 2020). "Both the ALDH2 gene and alcohol consumption are known risk factors associated with esophageal cancer." (PMID 30792419, 2019). "Informing ALDH2-deficient young people of their risk of esophageal cancer from alcohol drinking represents a valuable opportunity for cancer prevention." (PMID 33748520, 2018). "Existing evidence remains inconclusive as to how the association between inactive ALDH2 and esophageal cancer (EC) depends on alcohol consumption." (PMID 29707772, 2018). "Overall, literature provides strong evidence to support the synergistic interaction between ALDH2*2 allele and alcohol consumption to increase the risk of esophageal cancer." (PMID 28253921, 2017). "Case-control studies of various Japanese drinking populations and Chinese alcoholics have consistently reported that the inactive ALDH2 encoded by the ALDH2*1/2*2 genotype is a strong risk factor for esophageal cancer." (PMID 29299137, 2017). "One of the recent meta-analysis study among Japanese population indicated Glu504Lys polymorphism of ALDH2 gene as a candidate for susceptibility to esophageal cancer." (PMID 28805741, 2017). "There is a strong association between ALDH2 Glu487Lys polymorphism and the risk of esophageal cancer." (PMID 29299137, 2017). "Several other studies show a significantly increased risk of esophageal cancer for Asian individuals who are heavy or moderate drinkers and carry ALDH2*1/*2 or ALDH2*2/*2 genotype compared to those who have an ALDH2*1/*1 genotype." (PMID 28805741, 2017). "Patients with second primary pharyngeal and esophageal cancers according to p16-status and ALDH2 polymorphism." (PMID 29206831, 2017). "The dysfunctional A allele of ALDH2 has been associated with risks for many diseases, including esophageal cancer, coronary artery diseases, Alzheimer’s disease, diabetes, stroke, and others." (PMID 27927211, 2016).
esophageal cancer (continued). "One option to consider is more frequent screening for esophageal cancer for those with both the ALDH2*2 variant and a history of smoking cigarettes and/or consuming alcohol." (PMID 27835996, 2016). "Defective ALDH2 exhibits accelerated risk of progression of gastrointestinal cancers such as gastric cancer, esophageal cancer and colon cancer but its role in the liver, the major organ of alcohol metabolism, is still controversial." (PMID 26937962, 2016). "ALDH2-deficient heavy drinkers have been shown to have an over 100-fold higher risk of esophageal cancer." (PMID 25831092, 2015). "The polymorphism of the ALDH2 gene plays a central role in Asian alcohol hypersensitivity and has been associated with the risk for esophageal cancer." (PMID 26542211, 2015). "If they are heavy drinkers, their risk of oral, pharyngeal, and esophageal cancers is over 10-fold higher than in drinkers with the normal ALDH2 enzyme." (PMID 25831092, 2015). "Our results indicated that the ALDH2 Glu504Lys polymorphism is a susceptible loci associated with overall cancers, especially esophageal cancer and among Japanese population." (PMID 25680115, 2015). "In conclusion, this meta-analysis indicated that the Glu504Lys polymorphism of ALDH2 gene is a candidate for susceptibility to overall cancers, especially in esophageal cancer and among Japanese population." (PMID 25680115, 2015). "In alcohol drinkers, ALDH2-deficiency is a well-known risk factor for upper aerodigestive tract cancers, i.e., head and neck cancer and esophageal cancer." (PMID 25831092, 2015). "Another genome-wide association study reported that variations of ADH1B rs1229984 and ALDH2 rs671 coupled with alcohol drinking and smoking synergistically enhanced the risk of esophageal cancer." (PMID 24485404, 2014). "The ALDH2 rs671 A allele (slow type) has been associated with increased risk of head and neck cancer, as well as esophageal cancer." (PMID 25337902, 2014). "Among three ALDH2 SNPs, rs671 was associated with esophageal cancer in the recessive genetic model (A/A versus any G, SBOR: 1.76, 95% posterior limits: 0.96, 3.24)." (PMID 25337902, 2014). "A recent genome-wide association study identified the variation of ADH1B rs1229984 and ALDH2 rs671 polymorphisms as risk factors for esophageal cancer." (PMID 24485404, 2014). "In stratified adjusted analyses, ALDH2 rs671 appeared associated with esophageal cancer among individuals with lower plasma folate levels (A/A versus any G, SBOR: 2.12, 95% posterior limits: 1.01, 4.44)." (PMID 25337902, 2014). "For example, a deficiency in ALDH2 activity in people carrying a gene variant (i.e., allele) called ALDH2 Lys487 contributes to an elevated risk of esophageal cancer from alcohol consumption." (PMID 24881324, 2013). "Thus, MCV is likely to be most valuable as predictive factor for the onset of esophageal cancer in East Asian countries where the frequency of ALDH2 polymorphisms is similar to that of Japanese." (PMID 39932963, 2025). "In Japan (a population with esophageal squamous cell carcinoma as the predominant form of esophageal cancer, with smoking and alcohol use as risk factors), genomic analysis determined germline polymorphisms in ALDH2 and CYP2A6, which affect alcohol and tobacco metabolism." (PMID 39859964, 2024). "Since ALDH2*2 is the dominant negative, drinkers with heterozygosity of ALDH2*1 and ALDH2*2 are at significantly high risk of alcohol-related cancers within the upper aerodigestive tract, such as oropharyngeal, hypopharyngeal, and esophageal cancers." (PMID 38894937, 2024). "According to an association study of ADH1B and ALDH2 polymorphisms, East Asian populations may be more susceptible to the carcinogenic effect of alcohol, including esophageal cancer and head and neck cancer." (PMID 35670037, 2023).
esophageal cancer (continued). "The results of all Japanese and Chinese case–control studies on the association between esophageal cancer and ALDH2 heterozygotes deficiency showed that ALDH2 heterozygous deficiency increased the risk of esophageal cancer in drinkers (5.3–16.4 times the adjusted odds ratio)." (PMID 36028843, 2022). "The potential cause might be the high prevalence of ALDH2*2 allele in East Asians, and the evidence of the carcinogenic effect is strong in esophageal cancer and head and neck cancer." (PMID 35523974, 2022). "Therefore, the present study aimed to evaluate the association between ALDH2 rs671 polymorphisms and the risk of esophageal cancer in South Koreans." (PMID 33750341, 2021). "Moreover, case-control studies and a prospective cohort study suggested an association between ALDH2 rs671 polymorphisms and esophageal cancer." (PMID 33750341, 2021). "ALDH2 rs671 polymorphisms are associated with esophageal cancer in Eastern Asians." (PMID 33750341, 2021). "In Eastern Asians, ALDH2 rs671 polymorphisms are associated with esophageal cancer, which may be linked to acetaldehyde accumulation." (PMID 33750341, 2021). "Notably, individuals with ALDH2 GA/AA genotypes who consumed alcohol were at a particularly high risk of esophageal cancer, presumably due acetaldehyde accumulation in the esophagus." (PMID 33750341, 2021). "The fact that ALDH2*2 mutation is a double edged sword that increases both susceptibility to certain upper respiratory tract/esophageal cancers and can also limit the amount of cisplatin, may be useful information in the context of cisplatin treatment." (PMID 28532411, 2017). "This showed that even with the amount of alcohol considered as “light” or “moderate” drinking, the increase in esophageal cancer risk could be substantial for carriers of ALDH2*2 allele." (PMID 28253921, 2017). "This interaction between alcohol consumption and the ALDH2 genotype has been established to contribute to the risk of esophageal cancer, and in the aerodigestive tract, the effects of alcohol on esophageal, stomach, and colorectal cancers are expected to differ." (PMID 28036260, 2017). "In Taiwan and Japan, 65%–76% of esophageal cancer patients carried the ALDH2 risk alleles." (PMID 28562351, 2017). "These discussions could include how the ALDH2*2 variant in combination with lifestyle choices such as drinking alcohol or smoking cigarettes increases the relative risk of developing esophageal cancer." (PMID 27835996, 2016). "Further, screening for the ALDH2*2 gene could be used as topic of conversation with patients as a preventative measure to reduce esophageal cancer risk." (PMID 27835996, 2016). "With this in mind, people with an ALDH2*2 variant are at a much greater risk for esophageal cancer." (PMID 27835996, 2016). "Interestingly, the enlarged exposure to acetaldehyde in patients with a catalytically inactive form of Aldh2 has previously been shown to confer an increase susceptibility to many types of cancer, including esophageal cancer." (PMID 27565572, 2016). "ALDH2 has been demonstrated to be highly associated with the prognosis and chemoradiotherapy sensitivity of many types of cancer, including leukemia, lung cancer, head and neck cancer, esophageal cancer, hepatocellular cancer, pancreatic cancer, and ovarian cancer." (PMID 35517510, 2022). "Moreover, differences in exposure to salivary acetaldehyde among individuals with distinct genotypes may impact the effect of the ALDH2 genotype on esophageal cancer risk." (PMID 33750341, 2021). "Alcohol consumption is a major risk factor for esophageal cancer; however, a high incidence of esophageal cancer is observed particularly among Eastern Asians, although they consume relatively less alcohol, presumably due to the high frequency of aldehyde dehydrogenase 2 (ALDH2) rs671 polymorphisms." (PMID 33750341, 2021).